EGFR (epidermal growth factor receptor)
Diseases named in the same sentence as EGFR in open-access papers (continued):
Sharing a sentence is not in itself a finding about the gene and the disease.
pneumonitis (continued). "Moreover, previous studies indicated that the use of immune checkpoint inhibitors increases the risk of drug-induced pneumonitis if various tyrosine kinase inhibitors such as EGFR-TKIs were previously administered." (PMID 34497761, 2021). "The mechanism underlying osimertinib‐induced pneumonitis is unclear, but it has been reported that EGFR‐TKIs may increase the effects of lung damage by impairing alveolar repair mechanisms." (PMID 32666714, 2020). "However, the biological characteristics associated with EGFR-TKI-induced pneumonitis are yet to be determined." (PMID 31426531, 2019). "Furthermore, the risk of pneumonitis may increase when ICIs are used in combination with epidermal growth factor receptor-tyrosine kinase inhibitors (EGFR-TKI) NSCLC." (PMID 40145913, 2025). "In addition, osimertinib may be associated with a higher frequency of pneumonitis than first- and second-generation EGFR-TKIs32." (PMID 34848786, 2021). "The Phase I CHRYSALIS trial, which evaluated amivantamab in 362 patients with EGFR exon 20 insertion-mutated NSCLC, reported an incidence of 3.3% for all-grade pneumonitis, with 0.7% of patients experiencing grade 3 or higher events." (PMID 40805219, 2025). "In severe cases of EGFR-TKI induced pneumonitis, the therapeutic approach is either drug withdrawal or treatment with corticosteroids to reduce side effects." (PMID 41425704, 2025). "In the Phase I CHRYSALIS trial evaluating amivantamab in EGFR exon 20 insertion-mutated NSCLC, there was an incidence of 3.3% for all-grade pneumonitis, with 0.7% of patients experiencing grade 3 or higher events." (PMID 40805219, 2025). "Specifically, patients treated with osimertinib (EGFR-TKI), followed by a PD-1 or a PD-L1 inhibitor, are at a high risk of pneumonitis." (PMID 40145913, 2025). "Turning to oncogene-addicted disease, the phase III SINDAS trial revealed only a modest excess of severe pneumonitis when SBRT was added to first-generation EGFR-TKIs." (PMID 41008825, 2025). "Clinically, ICI-pneumonitis often presents earlier (median onset: 2.1–4.6 months) than EGFR-TKI-ILD and exhibits radiographic patterns such as cryptogenic organizing pneumonia more frequently." (PMID 40949116, 2025). "For example, the overall incidence of pneumonitis among NSCLC patients treated with epidermal growth factor receptor (EGFR) tyrosine kinase inhibitors is around 1%." (PMID 40805219, 2025). "While treating these patients, the administration of osimertinib, a third-generation EGFR inhibitor, after immunotherapy can lead to unique immune-related adverse events (irAEs), such as pneumonitis and, rarely, hepatitis." (PMID 40700234, 2025). "The BsAb amivantamab (targeting tumor-associated antigens EGFR and cMet) appears to have similar rates of pneumonitis compared to other EGFR inhibitors used in NSCLC treatment." (PMID 40805219, 2025). "While pulmonary toxicities (including pneumonitis and ILD) associated with EGFR-TKIs are rare, these can be severe." (PMID 39302574, 2024). "Given these perspectives, the choice of EGFR-TKIs for older patients should be based not only on survival but also on a lower incidence of pneumonitis than with osimertinib." (PMID 37179737, 2023). "A higher incidence of pneumonitis has been observed during the combination therapy of ICIs with other antitumor drugs, such as chemotherapeutic drugs and EGFR tyrosine kinase inhibitors (TKIs)." (PMID 35464480, 2022). "They reported that 18 of the 70 patients who were treated with the combination developed pneumonitis (25.7%), with the order of treatment in 15 patients identified as EGFR‐TKI after nivolumab administration." (PMID 33201587, 2021). "Despite the accumulating data and knowledge of EGFR-TKI-related pneumonitis, many issues remain to be solved." (PMID 33466795, 2021).
pneumonitis (continued). "EGFR-TKIs are administered to patients with NSCLC who had EGFR-activating mutations, and careful attention should be paid to patients with COPD, pneumonitis, pneumonia, and inflammatory cytokine-enriched circumstances when selecting EGFR-TKI treatment." (PMID 33466795, 2021). "Previous data suggest that Japanese patients are more likely to develop pneumonitis than patients of other nationalities when treated with EGFR-TKIs." (PMID 33648453, 2021). "Thirteen of 18 cases of pneumonitis treated with both EGFR-TKIs and nivolumab developed after the discontinuation of nivolumab." (PMID 32944393, 2020). "Similar to other EGFR‐TKIs, osimertinib‐induced pneumonitis has been reported at rates of 2%–4% across clinical trials, and drug‐induced pneumonitis can result in death." (PMID 32666714, 2020). "We herein describe a case of a 53-year-old patient with metastatic EGFR-mutated NSCLC, who developed pneumonitis after osimertinib treatment and was successfully rechallenged with 40 mg daily osimertinib, with CNS response." (PMID 31921341, 2019). "Although EGFR-TKIs are promising therapeutics for EGFR mutation-positive patients, it should be carefully administered to patients with accompanying COPD, pneumonitis, and pneumonia, and enrichment of inflammatory cytokines." (PMID 31426531, 2019). "For understanding the development of pneumonitis in whole lung, it is essential to evaluate lung inflammation by EGFR-TKI gefitinib administration ex vivo." (PMID 31426531, 2019). "Toxic deaths were rare at 1.7%, and pneumonitis emerged as the most common severe form of toxicity as it accounted for more than half the toxic deaths following the administration of EGFR-TKIs." (PMID 31426531, 2019). "Drug-related pneumonitis can also occur with chemotherapy (docetaxel, gemcitabine, bleomycin), targeted therapy (e.g. EGFR inhibitors, mTOR inhibitors), and radiation therapy." (PMID 30176946, 2018). "The grade 3 pneumonitis for patients treated with concurrent EGFR-TKI and chemoradiation is historically in the range of 6–8%." (PMID 23984359, 2013). "While EGFR-TKI-associated ILD primarily arises from direct epithelial injury and pro-fibrotic signaling in genetically susceptible hosts, ICI-related pneumonitis stems from T-cell-mediated inflammation and dysregulated immune responses." (PMID 40949116, 2025). "Notably, despite the widespread use of corticosteroid therapy in clinical practice, fatal cases of EGFR-TKI-induced pneumonitis continue to be reported in recent years." (PMID 41585870, 2025). "Similarly, other EGFR-TKIs, such as erlotinib and osimertinib, exhibited a higher frequency of drug-induced pneumonitis during molecular-targeted therapies in NSCLC with comorbid IP compared with those without IP." (PMID 38611005, 2024). "In addition, there should be increased attention on adverse events and potential additive toxicities such as pneumonitis, which was seen in previous sequencing of EGFR tyrosine kinase inhibitors and ICIs." (PMID 39199689, 2024). "The ATLANTIC study also demonstrated this, with durvalumab given for EGFR or ALK positive or negative NSCLC causing at least one fatal adverse event from pneumonitis." (PMID 37124513, 2023). "Patients with intermediate and high GRSs seem to be more likely to develop resistance to EGFR-TKIs and may have a high risk of developing EGFR-TKI-induced adverse events such as pneumonitis." (PMID 35372081, 2022). "In addition, patients with advanced NSCLC who were previously treated with nivolumab, a programmed death-1 (PD-1) inhibitor, developed severe pneumonitis during EGFR-TKI administration." (PMID 33466795, 2021). "Furthermore, the phase I CheckMate012 trial investigated erlotinib in combination with nivolumab in EGFR mutant patients and reported multiple incidences of pneumonitis and hepatic toxicities." (PMID 34001994, 2021).
pneumonitis (continued). "The incidence rates for EGFR-TKI treatment-related toxicity are higher among the Japanese than in other races, but the reason why Japanese NSCLC patients are susceptible to EGFR-TKI-induced pneumonitis is not clear." (PMID 31426531, 2019). "This study was performed to verify the hypothesis that EGFR-TKIs induce pneumonitis by blocking EGFR transactivation by TNF." (PMID 31426531, 2019). "Additionally, sequencing the novel agents with our current FDA-approved agents may lead to unforeseen complications, as was seen with the higher rates of pneumonitis with EGFR TKIs after immune checkpoint inhibitors." (PMID 37370772, 2023). "Several subgroup analyses yielded statistically significant intergroup differences in PFS but not in OS, including body mass index < 18.5, pneumonitis not requiring steroid treatment, and unknown EGFR mutation or ALK rearrangement." (PMID 36900397, 2023). "Increased body mass index, concurrent chemotherapy, epidermal growth factor receptor (EGFR) mutations, increased age, preexisting ILD, tumor infiltration, and concurrent obstruction of central airways are risk factors for early (less than 3 months) occurrence of pneumonitis." (PMID 35838354, 2022). "Notably, six patients opted to switch to EGFR TKI after experiencing PD on CRT + durvalumab and one of these patients developed Grade 4 pneumonitis 17 days after initiating osimertinib, again highlighting the safety signal of initiating EGFR TKIs after ICI therapy." (PMID 34868953, 2021). "Therefore, for cases of EGFR TKI-induced pneumonitis, EGFR tyrosine kinase activity may be required to maintain homeostasis in TNF-rich lung environments where chronic inflammation is present." (PMID 31426531, 2019). "In the OAK study, patients baseline characteristics include more EGFR KRAS mutation positive and ALK fusion positive patients, those patients who receive previous treatment with tyrosine kinase inhibitor are more likely to experience pneumonitis and lung inflammation." (PMID 30618738, 2018). "Therefore, this may be a plausible explanation for pneumonitis in the early studies with Brigatinib as it inhibits EGFR kinases." (PMID 29774128, 2018). "The study discovered that the odds ratio for an adverse event in treatment with an EGFR-TKI and nivolumab was 5.09 with 18 out of 70 patients developing pneumonitis." (PMID 37124513, 2023). "Dacomitinib, as an EGFR-TKI medication, may induce drug-induced pneumonitis; however, the patient’s imaging features (limited to the radiotherapy target area) are more consistent with the characteristics of radiation pneumonitis." (PMID 40071087, 2025). "This study was conducted with 20,516 patients to determine the frequency of TKI pneumonitis with or without nivolumab treatment for EGFR positive NSCLC lung cancer." (PMID 37124513, 2023). "In the present trial, we observed one case of severe pneumonitis due to treatment with anti-EGFR ILs-dox, which has not been reported previously." (PMID 34998092, 2022). "Japanese patients are predisposed to EGFR-TKI-induced lung injury compared to people of non-Japanese origin, and the odds ratio of all pneumonitis was 5.04 and that of grade 5 pneumonitis (death) was 4.55." (PMID 36499351, 2022). "It was interesting that pneumonitis was not reported in this study and is in contrast to findings seen with gefitinib, another EGFR tyrosine kinase inhibitor." (PMID 22240796, 2012). "One patient had disease progression early after the administration of EGFR‐TKI, and another patient who was administered EGFR‐TKI could not have their response assessed due to an adverse event of pneumonitis." (PMID 33314600, 2021). "The rates after conventional EGFR-TKI treatment were 4% in the AURA3 study and 7.3% in the Japanese subset of patients, which suggests that Japanese patients may have a higher rate of pneumonitis." (PMID 32517152, 2020). "The mechanisms of EGFR-TKI-induced pneumonitis have not been completely elucidated." (PMID 31426531, 2019).
pneumonitis (continued). "The pathophysiology of EGFR-TKI-related pneumonitis has not been elucidated, although a recent observation from a clinical combination trial of a novel immune-checkpoint inhibitor (ICI) and third-generation EGFR-TKI, Osimertinib, raised concerns with regard to lung toxicity." (PMID 33466795, 2021).
pancreatic ductal adenocarcinoma (65 papers, 2007 to 2026). An infiltrating adenocarcinoma that arises from the epithelial cells of the pancreas. "The activation of STAT3 in pancreatic ductal adenocarcinoma is associated with autocrine and/or paracrine epidermal growth factor receptor signalling, since the selective inhibition of epidermal growth factor receptor results in a loss of activated STAT3 expression." (PMID 37108193, 2023). "Notably, a high expression of FASN has been linked to poor prognosis of pancreatic ductal adenocarcinoma patients and depends heavily on induction of EGFR/ERK signalling." (PMID 29385093, 2018). "Epidermal growth factor receptor (EGFR) is a pivotal therapeutic target in pancreatic ductal adenocarcinoma (PDAC); however, the clinical efficacy of tyrosine kinase inhibitors (TKIs) such as erlotinib is frequently curtailed by acquired resistance." (PMID 42088423, 2026). "TGF‐β‐activated epidermal growth factor receptor signaling in myCAFs contributes to the promotion of tumor growth and metastasis of pancreatic ductal adenocarcinoma (PDAC)." (PMID 40644310, 2025). "Targeted therapies are diversifying treatment options in pancreatic ductal adenocarcinoma; however, numerous studies have also attempted to target other related signaling molecules, such as EGFR, MEK, and PI3K." (PMID 39592929, 2024). "There are several receptors and pathways associated with the development of pancreatic ductal adenocarcinoma (PDAC), including the EGFR, the receptor protein tyrosine kinase, the NOTCH signaling system, the ERBB2, and the TGF bate pathway." (PMID 38532833, 2023). "In this study, a platform was developed that utilized EGFR targeting to bring the bioluminescent protein Gaussia luciferase to pancreatic ductal adenocarcinoma cells for imaging and identification by using a dendrimer as a nanocarrier." (PMID 37514162, 2023). "For example, activated epidermal growth factor receptor (EGFR) was shown to upregulate FASN in pancreatic ductal carcinoma and reciprocally, silencing or inhibition with small molecule inhibitor Erlotinib abolished FASN upregulation." (PMID 35323656, 2022). "Strikingly, ADAM17 and ERBB1/EGFR are both required to maintain high RAS activity in a KrasG12D mouse model of pancreatic ductal carcinoma." (PMID 35971826, 2022). "Hasan T coupled epidermal growth factor receptor (EGFR) monoclonal antibody Cetuximab with benzoporphyrin derivative for pancreatic ductal adenocarcinoma treatment." (PMID 34834367, 2021). "For example, KRAS-mutant pancreatic ductal adenocarcinoma (PDAC) activates the epidermal growth factor receptor (EGFR) by inducing an autocrine feed-loop and amplifies the signals required for PDAC development." (PMID 34136473, 2021). "YAP plays a crucial role in KRAS-mutation-driven tumorigenesis of pancreatic ductal adenocarcinoma, and we previously identified that YAP/TAZ expressions participate in the resistance of anti-EGFR therapy in KRAS-mutant NSCLC." (PMID 34073318, 2021). "Clinical trials of EGFR inhibitors in combination with gemcitabine for the treatment of pancreatic ductal adenocarcinoma (PDAC) have generated mixed results partially due to the poorly defined effectiveness of EGFR inhibitors in PDAC." (PMID 30921351, 2019). "Activation of EGFR and its downstream pathways is a significant event in the formation of pancreatic ductal adenocarcinoma (PDAC), reinforcing ERK pathway activation to promote tumor transformation after the initial driver mutation(s) occur in KRAS." (PMID 30921351, 2019). "A recent study on human pancreatic ductal adenocarcinomas validated that low c-CBL was associated with shorter survival, and had an inverse correlation with levels of epidermal growth factor receptor." (PMID 27472394, 2016). "We retrospectively investigated EGFR status in 357 resected PDAC (pancreatic duct adenocarcinoma) patients using tissue immunohistochemistry and validated the possible role of EGFR expression in predicting prognosis." (PMID 27399694, 2016).
pancreatic ductal adenocarcinoma (continued). "Cyclooxygenase-2 (COX-2), 5-Lipoxygenase (5-LOX), and epidermal growth factor receptor (EGRF) are over-expressed in human pancreatic ductal adenocarcinoma (PDAC)." (PMID 26429877, 2015). "Epidermal growth factor receptor (EGFR) is highly expressed in pancreatic ductal adenocarcinoma (PDAC) and is involved in tumorigenesis and development." (PMID 25679210, 2015). "Therefore, the purpose of our study is to examine the expression of markers such as EGFR, Cyclin D1, andCDK4 in order to find a relationship with the possible long-term prognostic factors of patients affected by pancreatic ductal adenocarcinoma." (PMID 35448172, 2022). "In pancreatic ductal carcinoma, EGFR is overexpressed in 30–89% of the cases." (PMID 33937024, 2021). "Importantly, in KRAS-induced murine tumor models, EGFR signaling is essential for KRAS oncogene-driven pancreatic ductal adenocarcinoma." (PMID 29156578, 2017). "In addition, the expression of EGFR was reported in conjunction with insulinlike growth factor 1 receptor (IGF-1R) to predict poor survival in pancreatic ductal adenocarcinoma." (PMID 27399694, 2016). "While some EGFR inhibitors like erlotinib and nimotuzumab have shown efficacy, others have failed to yield significant results in clinical trials for pancreatic ductal adenocarcinoma, suggesting potential resistance mechanisms within pancreatic ductal adenocarcinoma to EGFR inhibitors." (PMID 39592929, 2024). "Moreover, clinical observations indicate that pancreatic ductal adenocarcinoma may activate alternative signaling pathways to circumvent EGFR inhibition, further reducing the efficacy of therapies that target only EGFR." (PMID 39592929, 2024). "Indeed, Mist1 silencing is one of the first events associated with Kras-induced pancreatic ductal adenocarcinoma (PDAC) with MIST1 negative acinar cells exhibiting early activation of EGFR signaling and downstream MAPK pathways." (PMID 26717480, 2015). "Sialyl-Tn expression on MUC16 enhances the aggressive phenotype of pancreatic ductal adenocarcinoma (PDAC) tumor cells, increasing epidermal growth factor receptor (EGFR) interactions and triggering AKT and glycogen synthase kinase-3β oncogenic signaling." (PMID 40885395, 2025). "Given that pancreatic ductal cells are the cells of origin for pancreatic ductal adenocarcinoma (PDAC), manipulating key signalling pathways such as EGFR, Notch, and YAP carries potential oncogenic risks." (PMID 40236756, 2025). "For instance, in pancreatic ductal adenocarcinoma (PDAC), TGF-β-induced AREG activates EGFR by phosphorylation at Tyr1068 and promotes PDAC metastasis." (PMID 39451251, 2024). "Knockdown of O-glycosyltransferase GALNT3 resulted in increasing the expression of poorly differentiated pancreatic ductal adenocarcinoma (PDAC) markers and influencing the O-glycans (Tn and T) expression in EGFR and Her2 in PDAC cells." (PMID 31355147, 2019). "Treatment with epidermal growth factor receptor (EGFR) inhibitors can result in clinical response in non-small-cell lung cancer (NSCLC) and pancreatic ductal adenocarcinoma (PDAC) for some unselected patients." (PMID 22045191, 2012). "The insufficient levels of CBL have been identified as a factor contributing to the development of chemotherapy resistance in pancreatic ductal adenocarcinoma (PDAC), which is attributed largely to the stress-induced activation of EGFR (epidermal growth factor receptor)." (PMID 39130630, 2024). "As bone tumors in H2‐c‐fosLTR mice arise from the osteoblastic lineage, we hypothesize that the tumor cell‐intrinsic function of EGFR might be similar to its role in pancreatic ductal adenocarcinoma (PDAC), where EGFR deletion or inhibition was shown to ameliorate KRAS‐driven PDAC." (PMID 30361264, 2018).